MAGEB16 (MAGE family member B16)
Tractability: No criterion of Open Targets' tractability assessment is met for any kind of drug.
Gene: Protein-coding gene on chromosome X (35,798,342 to 35,803,772, forward strand). Ensembl gene ENSG00000189023.
Subcellular location (Human Protein Atlas): Nucleoplasm; Centrosome
Gene Ontology:
Biological process: negative regulation of transcription by RNA polymerase II
Cellular component: nucleus; cytoplasm
Homologues: Orthologues: chimpanzee MAGEB16 (97% identical), rabbit MAGEB16 (67% identical), mouse Mageb16 (54% identical), rat Mageb16 (54% identical), zebrafish ndnl2 (28% identical), Drosophila melanogaster MAGE (21% identical). Paralogues in human: MAGEB18 (50% identical), MAGEA10 (49% identical), MAGEB10 (48% identical), MAGEA11 (47% identical), MAGEB4 (47% identical), MAGEB17 (46% identical), MAGEB3 (46% identical), MAGEB1 (46% identical), MAGEA4 (46% identical), MAGEA9 (46% identical), MAGEA9B (46% identical), MAGEA8 (45% identical), and 25 more.
Diseases named in the same sentence as MAGEB16 in open-access papers:
MAGEB16 is named in the same sentence as 9 diseases in open-access papers, as found by Europe PMC text mining. Sharing a sentence is not in itself a finding about the gene and the disease. The quoted sentences say what the papers report.
autism spectrum disorder (1 paper, 2026). A spectrum of developmental disorders that includes autism, and Asperger syndrome. "In addition to its established roles in spermatogenesis and oncogenesis, emerging functional, epigenomic, and genetic evidence points to MAGEB16 as an epigenetically sensitive modifier of early developmental programs implicated in neurodevelopmental disorders such as Autism Spectrum Disorder (ASD)." (PMID 41988164, 2026).
chondrosarcoma (1 paper, 2012). A malignant cartilaginous matrix-producing mesenchymal neoplasm arising from the bone and soft tissue. "Also interestingly, Mageb16 is expressed in a rat chondrosarcoma cell line of which the corresponding normal cartilage tissue does not express Type I MAGEs." (PMID 23133577, 2012).
cancer (2 papers, 2016 to 2021). A tumor composed of atypical neoplastic, often pleomorphic cells that invade other tissues. "Besides, the mRNA expression of MAGEB16, SERPINE1, HSPA2, FOS, involved in the cancer-related signaling pathways, was 1.64, 2.83, 3.62, 2.54 fold changed respectively." (PMID 26879937, 2016).
MAGEB16 also shares sentences with these, for which no sentence is quoted: bladder cancer (1 paper); colorectal cancer (1); gastric cancer (1); neurodevelopmental disorder (1); thrombosis (1); tumor diseases (1).